INS (insulin)
Diseases named in the same sentence as INS in open-access papers (continued):
Sharing a sentence is not in itself a finding about the gene and the disease.
Hypoglycemia (continued). "Therefore, they can potentially reduce the hypoglycemia that occurs after an insulin spike." (PMID 36748934, 2023). "At weaning, TCDD caused hypoglycemia in male offspring but did not affect random-fed blood glucose levels in female offspring, body weight in either sex or random-fed plasma insulin levels in either sex." (PMID 37115651, 2023). "In addition, SUs and glinides stimulate insulin secretion in the absence of glucose or food uptake, which can cause hypoglycemia, a major side effect that can limit their use for some patients." (PMID 36980281, 2023). "(Left side) In the low-fat/high-exercise condition as seen in pre-modern lives, glucose effectiveness, an insulin-independent mechanism of glucose disposal, becomes high, which is associated with frequent mild hypoglycemia without typical symptoms (thus, subclinical) after meals." (PMID 37367911, 2023). "Besides, sulfonylureas could increase insulin release from pancreatic beta cells by acting on ATP-sensitive potassium channels, leading to hypoglycemia." (PMID 37024869, 2023). "At the same time, continuous insulin release can be achieved without the risk of hypoglycemia." (PMID 36839676, 2023). "Current research supports the use of GLP1-RA in combination with a lower dose of insulin to more effectively reduce HbA1c while mitigating weight gain from insulin and lowering the risk of hypoglycemia, all with no change in adverse gastrointestinal issues from the use of GLP1-RA independently." (PMID 37090383, 2023). "Although the physiologic basis of BG and IG discrepancy is expected to be the same regardless of cause of hypoglycemia, further study is required to validate these findings in client‐owned diabetic cats, in insulin‐independent hypoglycemic syndromes, and in other species." (PMID 37534946, 2023). "A meta-analysis of studies of the combination of a DPP-4i and insulin, in adult patients with latent autoimmune diabetes, reported improved glycemic control, increased islet beta-cell cell function, and decreased incidence of hypoglycemia compared with insulin treatment alone." (PMID 37293502, 2023). "Therefore, patients need to administer insulin 30 min before a meal, but there is a risk of hypoglycemia if patients do not eat 30 min after receiving insulin." (PMID 37239127, 2023). "However, if HbA1c overestimates the MBG of youth with diabetes living in Africa, as it does for African diaspora populations, then treatment to HbA1c target might lead to inadvertent over prescription of insulin and more frequent occurrence of hypoglycemia." (PMID 38706529, 2023). "Maternal obesity influences the composition of breast milk, and the present results confirm the previous observation that the breast milk of obese mothers contains a higher insulin concentration, raising the question of whether this may contribute to neonatal hypoglycemia." (PMID 36986206, 2023). "Conditioning with insulin might trigger conditioned insulin release and glucose decrease without causing common adverse effects of intravenous insulin injections such as hypoglycemia and hypertension." (PMID 37234022, 2023). "Moreover, the regulatory mechanism of SGLT-2 inhibitors is insulin-independent; hence, there is generally no risk of hypoglycemia, and it protects β-cells from glucose toxicity." (PMID 37686185, 2023). "Other child or family factors may play a role, including early morning eating habits, activities, school or home-related stressors, or insulin dosing decisions to prevent hypoglycemia on the way to school, as parental fear of hypoglycemia may lead to practices to keep blood glucoses higher." (PMID 37929231, 2023). "Interestingly, we discovered that the risk of hypoglycemia caused by tirzepatide was reduced when it was administered without insulinotropic drugs or insulin." (PMID 37096236, 2023).
Hypoglycemia (continued). "When insulin is used in both the hospitalized and nonhospitalized setting, it is important to match the pharmacokinetics of the GC preparation with the precise insulin regimen in order to optimize glucose control and reduce the risk of hypoglycemia." (PMID 37253115, 2023). "Thus, we hypothesized that prolonged hypoglycemia and enhanced insulin sensitivity in GHR-KO pigs may lead to enhanced immune function, especially in CD4+ T cells." (PMID 37189345, 2023). "Although this may be sufficient to alert trained emergency personnel to consider a glycaemic event as a potential cause of the person’s state, misinterpretation by the lay person could have fatal implications if, for example, insulin was to be administered in the setting of hypoglycaemia." (PMID 36334194, 2023). "Also, there are potential, as in any observational study, known residual confounding factors, i.e. insulin dosing and frequency of hypoglycemia, and unknown residual confounding factors that could have affected our results." (PMID 36935526, 2023). "Additionally, the research suggested that the elevated fracture risk associated with HbA1c levels might be partially explained by hypoglycaemia-induced falls, potentially triggered by insulin use." (PMID 37968679, 2023). "This drug does not cause significant hypoglycemia or increase endogenous insulin secretion." (PMID 37854083, 2023). "In addition to daily glycemic control, reliance on acute hypoglycemia strategies, athletic performance, and well-being, the recovery phase strategies (i.e., ModCHO diet and 24 h insulin adjustments) and exercise strategies themselves are also part of the overall case study results." (PMID 37999431, 2023). "Furthermore, Insulin-induced hypoglycemia is one of the typical side effects of insulin treatment." (PMID 36974247, 2023). "GLP1 receptor agonists do not cause hypoglycemia; however, if a patient is already on insulin or a sulphonylurea, the doses of these may need to be reduced to avoid hypoglycemia." (PMID 37242585, 2023). "Hypoglycemia was induced by infusion of regular insulin, resulting in rapid BG shifts that might or might not be comparable to what is seen with intermediate‐ and long‐acting insulin formulations used in the home environment." (PMID 37534946, 2023). "Yet, intensive insulin therapy remained the standard approach, with only more recent recommendations regarding tailoring glycemic targets to individual needs based upon impaired awareness of hypoglycemia, co-morbidities, or individual characteristics suggestive of reduced survival." (PMID 37794113, 2023). "While existent strategies for athletic performance in T1DM are primarily focused on acute (i.e., pre- and during exercise) CHOsup and insulin dose reduction to prevent hypoglycemia during exercise, acute strategies may contribute to later deterioration of glycemic control in the athlete." (PMID 37999431, 2023). "However, we did not administer insulin in our protocols for safety reasons because hypoglycemia is also associated with poor neurologic outcomes, cardiovascular instability, and seizures." (PMID 37887298, 2023). "In addition, everolimus, an mTOR inhibitor, has been reported effective in controlling insulin-induced hypoglycemia in malignant insulinomas refractory to somatostatin analogues, and could be considered in this patient." (PMID 36835815, 2023). "There have been previous calls for researchers to identify the motivation underlying insulin restriction more carefully, as individuals with T1DM may restrict and/or omit insulin due to fear of injections, fear of hypoglycaemia, denial of disease and avoidance of injections in social settings." (PMID 37255778, 2023). "Therefore, patients with a congenital porto-systemic shunt present a unique combination of (a) postabsorptive hyperinsulinemic hypoglycaemia (HH) because of decreased insulin elimination and (b) fasting (ketotic) hypoglycaemia because of decreased glycogenolysis." (PMID 37664849, 2023).
Hypoglycemia (continued). "Furthermore, concomitant CGM and ECG monitoring for 3 days in insulin-treated T2D patients with coronary heart disease showed that chest pain was accompanied by ischemic changes in the ECG of some of the patients during hypoglycemia." (PMID 37298308, 2023). "Additionally, in vivo, a slightly increased insulin secretion during deactivation would be expected to lead to a slight further decrease in glucose concentration and accelerate beta cell deactivation before hypoglycemia would ensue." (PMID 38292770, 2023). "While non-machine learning algorithms such as Model Predictive Control have been beneficial for adults and neonates using closed loop insulin delivery, these systems are of no use to the majority of patients with rare hypoglycaemia disorders whose hypoglycaemia is not caused by exogenous insulin." (PMID 36755920, 2023). "By switching to a treatment regimen that excludes the use of sulfonylureas and insulin, type 2 diabetics may be able to lower their risk of hypoglycemia." (PMID 38022365, 2023). "However, this is a balancing act since overestimated insulin doses instead lead to hypoglycemia." (PMID 37739421, 2023). "Hence, the observed effect of genipin on insulin sensitivity could be at least partially due to suppressed hypoglycemia-induced glucagon secretion from the islets, which needs further investigation." (PMID 36768454, 2023). "However, in a normal dog with hypoglycemia, insulin levels are expected to be much lower." (PMID 38260191, 2023). "Our study showed that although insulin use might increase the risk of severe hypoglycemia, bacterial pneumonia, and ventilation use, it might not increase the risk of death in patients with T2D and COPD." (PMID 37242426, 2023). "During the hypoglycemic period after a meal in GDH-HI patients, the plasma insulin concentrations may be reduced, indicating that high insulin levels are not the only cause of hypoglycemia in GDH-HI patients." (PMID 36721237, 2023). "A high proportion of post-exercise hypoglycemia was expected for this population and intervention, but highlights a need for future trials to include participant education regarding modification and timing of insulin dose and carbohydrate consumption with exercise." (PMID 36835790, 2023). "Therefore, individuals with IAH may plan to loosen tight glucose management and intentionally omit insulin injection to prevent severe hypoglycemia (SH)." (PMID 37095537, 2023). "In contemporary ICUs, insulin therapy is commonly guided by intermittent blood gas glucose analyses, which has a significant impact on staff workload and may counteract timely recognition of hypoglycemia and attenuation of glucose variability." (PMID 36263915, 2023). "In addition, a basal insulin replacement higher than physiological need may result in fasting hypoglycemia and, therefore, the need for extra carbohydrate intake." (PMID 40303252, 2023). "However, after using a smaller dose of dapagliflozin (1.5 mg/d), this patient achieved better glycemia control, with a significant reduction in daily insulin dosage and gradual weight loss, without significant hypoglycemia or DKA occurring." (PMID 37241059, 2023). "Therefore, ingesting carbohydrates prior to aerobic exercise as well as reducing/withholding insulin doses might be a necessary strategy to avoid hypoglycemia." (PMID 36981876, 2023). "An insulin to glucose ratio was not consistent with insulinoma as a cause for hypoglycemia." (PMID 37143502, 2023). "Additionally, GhIRKO mice required reduced glucose infusion rates during hyperinsulinemic-hypoglycemic clamps, suggesting that suppressed ghrelin release resulting from direct insulin action on ghrelin cells usually limits ghrelin’s full potential to protect against insulin-induced hypoglycemia." (PMID 37334290, 2023).
Hypoglycemia (continued). "However, their use requires careful monitoring because they may inhibit not only ectopic insulin secretion but also the release of counterregulatory hormones, such as glucagon, which can worsen hypoglycemia in some patients." (PMID 37103745, 2023). "A strategy that appears to be effective is to split the insulin bolus into two different insulin delivery times (e.g. 10 minutes before and 1 hour after eating), to cover the extended postprandial period with increased insulin needs and to prevent early hypoglycemia." (PMID 37705724, 2023). "If insulin, in this one instance, were to inhibit gluconeogenesis and glycogenolysis, whilst facilitating oral glucose load myocyte uptake, a potential case of hypoglycaemia with hypoketonaemia and inhibition of beta-oxidation may simultaneously occur, which would be potentially fatal." (PMID 37958602, 2023). "For instance, a pregnant woman could interrupt her newly administered insulin because of concerns that it might harm her fetus, because of reoccurring hypoglycemia symptoms, or because it is inconvenient for her to inject it at work, on the train, or in a restaurant." (PMID 38200907, 2023). "Hypoglycemia is the most serious complication of insulin therapy; therefore, adjunctive leptin treatment could reduce the severity of these episodes; indeed, the combination of insulin and leptin in T1DM mice was shown to improve glycemic stability." (PMID 36674935, 2023). "Investigations revealed hypoglycemia with fasting blood glucose ranging between 33 mg% to 46 mg%, and high levels of postprandial glucose ranging between 299 mg% and 476 mg% in repeated measurement, insulin level was high (345 uIU/ml, N: 2–25 uIU/ml) and C-peptide levels (22 ng/mL)." (PMID 40041273, 2023). "Moreover, preoperative use of β-adrenergic blockers can lead to increased insulin production from pancreatic cells and to impair liver gluconeogenesis and the glucagon secretion mechanism, subsequently contributing to the development of hypoglycemia." (PMID 36982228, 2023). "Clinical trials are needed to determine whether insulin dose adjustments for protein intake following exercise are necessary or beneficial, as correcting insulin doses for protein in this context may hamper the potential benefit of dietary protein in preventing post-exercise hypoglycemia." (PMID 37836552, 2023). "Administration of LSML for four weeks prevented the blood glucose increase without causing hypoglycemia, which might be the effect of rapid recovery of pancreatic β-cells and restoration of the delayed insulin response." (PMID 36552606, 2022). "Beta-2 agonists may also be used in combination with insulin to promote a significantly greater fall in K+ levels than when either agent is individually administered and hypoglycemia is less likely to occur with the combined therapy than when insulin alone is used." (PMID 35466190, 2022). "The use of insulin in a dose higher than the therapeutic dose may result in hypoglycemia." (PMID 35324747, 2022). "Moreover, insulin and aloe vera have an additive blood-glucose-lowering effect, so their co-administration may provoke symptoms of hypoglycemia." (PMID 35409970, 2022). "In a study performed by Rosenstock at al., empagliflozin caused an improvement of glycemic control and weight reduction in obese patients with T2DM with inadequate control on high multiple dose insulin without increasing the risk of hypoglycemia and with lower insulin requirements." (PMID 36552050, 2022). "First, as the administration of insulin is via Subcutaneous (SC), that leads to open-label design and might be unable to avoid investigator and participants bias of reports especially on safety, such as hypoglycemia and adverse events." (PMID 35123455, 2022).
Hypoglycemia (continued). "Bolus calculators used during closed-loop may account only for the insulin on board from a previous bolus, and may not include any closed-loop insulin delivery in the bolus calculation, which can contribute to the risk of hypoglycemia with delayed bolusing." (PMID 32914648, 2022). "Glinides are short-acting insulin secretagogues that may not be as efficacious as sulfonylureas, but their shorter half-life and meal-time usage is associated with a lower risk of hypoglycemia." (PMID 34922811, 2022). "However, the treatment might not have been intensified and titrated effectively because of fear of adverse effects like hypoglycemia, and the need to educate patients about insulin administration and adverse effects would be mandatory." (PMID 35617250, 2022). "The hormone insulin, whether supplied orally or intravenously, maintains steady blood sugar levels all day, which helps eliminate carb counting, several regular injections, hypoglycemia, and high blood sugar." (PMID 36381916, 2022). "However, challenges of current insulin therapies, including narrow therapeutic index (TI) to hypoglycemia and body weight gain, limit their adoption and, when adopted, challenge patients’ ability to achieve ideal glycemic control as a consequence of underdosing due to fear of hypoglycemia." (PMID 35177603, 2022). "However, patients would have more comorbidities or DM-related complications when insulin is started, which could result in a high probability of hypoglycemia." (PMID 35055382, 2022). "Patient-related barriers represent about 30% of therapeutic inertia such as misconceptions regarding insulin risk, injection phobia, fear of weight gain, fear of hypoglycemia, negative impact on social life and job, poor health literacy, low self-efficacy and healthcare providers’ inadequacy." (PMID 36554673, 2022). "In addition, well-aligned and easily brushable teeth are more important in patients who live with DM: hypoglycemia occasionally results from intensive insulin therapy, and in this scenario, patients need to consume fast-absorbing carbohydrates, sugary drinks, or sugar." (PMID 35010805, 2022). "Analytical limitations in the quantification of insulin and C-peptide in blood samples create problems for using the ratio of insulin to C-peptide, an interesting hypothetical value that could be used to distinguish between hypoglycemia due to exogenous or endogenous insulin." (PMID 36359343, 2022). "Type 1 diabetic patients with exogenous insulin therapy are exposed to the risk of hypoglycemia, as their systemic insulin levels may not be reduced in time when the glucose levels begin to decline." (PMID 36619543, 2022). "Furthermore, the use of insulin may directly aggravate the psychological burden of patients and give patients psychological hints of hypoglycemia." (PMID 36434039, 2022). "The mean gestational weight gain and risk of maternal hypoglycaemia, hypertensive disorder, caesarean delivery, spontaneous abortion, endometritis and wound infection or dehiscence were similar among pregnant women with GDM managed using long-acting insulin analogues and NPH." (PMID 36271431, 2022). "Although people with T1D seem to be aware of the increased risk of nocturnal hypoglycemia associated with PA, the risk associated with additional insulin boluses may not be as clear." (PMID 36237197, 2022). "This “functional hypercortisolism” may help to antagonize insulin actions and in this way prevent both hypoglycemia and overstimulation of target tissues from nutrient-induced injury (see next paragraph entitled Evidence for insulin regulation of the HPA activity below for more details)." (PMID 35897752, 2022). "Moreover, patients with liver cirrhosis had an increased risk of hypoglycemia, regardless of age, sex, chronic kidney disease, insulin, sulfonylureas, and different types of sulfonylurea, number of oral hypoglycemic agents, β-blocker, and fibrate use." (PMID 36687427, 2022).